FASN (fatty acid synthase)
Diseases named in the same sentence as FASN in open-access papers (continued):
Sharing a sentence is not in itself a finding about the gene and the disease.
prostate tumor (continued). "The combined genomic and expression profiling analysis described in this study suggested an upregulation of FASN, BARK1, MYC, PP1α, and NM23-H1 expression and a downregulation of PP2A expression in prostate tumours." (PMID 17146477, 2007). "To assess epithelial FASN protein expression across a racially diverse JHU primary tumor cohort, we digitally quantified a validated FASN IHC assay in benign glands and primary prostate tumor epithelial cells." (PMID 38112617, 2024). "Though prostate tumors from HOXB13 G84E carriers are frequently low grade and indolent, these results may have therapeutic implications for the rare carriers who develop metastatic disease and who may benefit from FASN inhibitors." (PMID 38112617, 2024). "To test whether the inverse correlation between global FASN gene methylation and expression observed in primary tumors was generalizable to metastatic tumors and other methylation assays, we examined WGBS previously published for the SU2C WCDT metastatic prostate tumor samples." (PMID 38112617, 2024).
endometrial cancer (16 papers, 2013 to 2024). Primary or metastatic malignant neoplasm involving the endometrium (mucous membrane that lines the endometrial cavity). "A poor prognosis has been proven to be associated with the overexpression of FASN in endometrial cancer." (PMID 34016103, 2021). "Overexpression of fatty acid synthase is a common molecular feature of a subgroup of sex steroid-related cancers associated with poor prognoses, including endometrial cancers." (PMID 35008502, 2021). "Fatty acid synthase (FAS), a key lipogenic enzyme, is expressed in endometrial cancer tumors and is associated with a worse prognosis for this disease." (PMID 37601677, 2023). "FASN expression in endometrial cancer was also found to gradually increase as the endometrium advances from hyperplasia to carcinoma, suggesting the use of FASN as one of the molecular markers for histological staging." (PMID 35448537, 2022). "Such cases warrant caution in using FASN as a potential prognostic marker by considering the specific type of endometrial cancer." (PMID 35448537, 2022). "Recent studies also reported that multiple lncRNAs competitively bind miRNAs to regulate FASN expression in nasopharyngeal and endometrial cancer." (PMID 35392075, 2022). "We previously demonstrated that FASN blockade suppresses the well-documented capacity of estradiol to up-regulate PR expression in endometrial cancer cells." (PMID 33335078, 2020). "We previously reported that SREBP1 promoted fatty acid metabolism by regulating the transcription of FASN and played an important role in the tumorigenesis of endometrial cancer." (PMID 30813939, 2019). "Many tumors therefore express high levels of FASN, including breast, colorectal and endometrial cancers, and FASN inhibitors either kill tumor cells directly or sensitize them to other therapies such as 5-fluorouracil and trastuzumab (Herceptin)." (PMID 26130389, 2015). "FASN expression has been reported to correlate with Ki67 labelling index in human endometrial carcinomas." (PMID 23292678, 2013). "Thus, inhibiting FASN has been proposed as a therapy targeting estrogen receptor signaling in breast and endometrial cancer." (PMID 39020289, 2024). "Furthermore, FASN inhibition led to a marked decrease in E2-stimulated ER expression, suggesting a regulatory role for FASN in controlling ER levels in endometrial carcinoma cells." (PMID 37958433, 2023). "Interestingly, in endometrial cancer cell lines, the growth of high-ER-expressing Ishikawa cells was more retarded by FASN inhibition than that of low-ER-expressing HEC1B cells." (PMID 35448537, 2022). "Notably, this FASN inhibition also contributed to decreased cell proliferation and increased apoptosis, pointing toward its potential as a therapeutic target to modulate endometrial carcinoma progression and hormone-dependent signaling pathways." (PMID 37958433, 2023). "The enzyme fatty acid synthase (FASN), responsible for producing long-chain fatty acids, has varying effects on estrogen (E2) signaling in breast and endometrial carcinoma cells." (PMID 37958433, 2023). "Several studies have shown that fatty acid synthase (FASN), a key lipogenic enzyme catalysing the terminal steps in the de novo biogenesis of fatty acids, and SREBP1 are overexpressed in endometrial cancer." (PMID 29552293, 2018). "In addition, in endometrial cancer cell, SREBP1/FASN was suppressed during the proliferation suppression and apoptosis induced by progesterone." (PMID 30813939, 2019). "FASN also inhibits the expression of HER2 and may function as a potential therapeutic target in estrogen receptor- and progesterone receptor-positive endometrial cancers." (PMID 30237984, 2018).
leukemia (16 papers, 2014 to 2025). A malignant (clonal) hematologic disorder, involving hematopoietic stem cells and characterized by the presence of primitive or atypical myeloid or lymphoid cells in the bone marrow and the blood. "Furthermore, it is reported that fatty acid synthase (FASN) expression in a leukemia cell line is linked to an increase in PD-L1 expression, suggesting an immunosuppressive role of fatty acid synthesis." (PMID 35011741, 2022). "Quizartinib combined with SREBP inhibitor fatostatin or FASN inhibitor orlistat provided substantial therapeutic benefit over monotherapies in the murine FLT3/ITD leukemia model." (PMID 40263296, 2025). "Ginger extract, gallic acid, cerulenin, and ginkgolic acids have demonstrated promising success in inhibiting leukemia cells by diminishing the FASN activity." (PMID 37256177, 2023). "Interfering FASN expression by either RNAi or EGCG alleviates the effectiveness of differentiation therapy in leukemia." (PMID 37256177, 2023). "FASN is frequently overexpressed in a variety of tumor types including leukemias while its expression in healthy adult tissues is low, with the exception of the cycling endometrium and lactating breast." (PMID 33742137, 2021). "In this study, we determined that cerulenin, a natural product inhibitor of fatty acid synthase, induces mitochondrial injury and apoptosis in human leukemia cells through the mitochondrial translocation of cofilin." (PMID 26967395, 2016). "Pharmacological inhibition of SREBP1 or FASN sensitized FLT3/ITD leukemia cells to quizartinib." (PMID 40263296, 2025). "It was reported that FASN was overexpressed in a variety of cancers including leukemia." (PMID 40075508, 2025). "Fatty acid synthase (FASN) is another key regulator which may be responsible for leukaemia drug resistance." (PMID 33939282, 2021). "The increased FASN expression in cancers including leukemias, its function in tumor-associated myeloid cells and its link to the differentiation enhancer DAPK2 prompted us to analyze the regulation and function of FASN during myeloid leukemic differentiation." (PMID 33742137, 2021). "In addition, inhibition of fatty acid synthase activity may be a potential strategy for the treatment of leukemia." (PMID 40075508, 2025). "Therefore, our data suggests that targeting the oncogenic activation of FLT3/SREBP/FASN axis may be a more effective strategy to enhance the anti-leukemia effect of quizartinib." (PMID 40263296, 2025). "To evaluate the impact of FASN on FLT3-ITD signaling, we generated stable FASN knockdowns via shRNA in two human leukemia cell lines, MOLM13 and MV411." (PMID 40565186, 2025). "A new FASN inhibitor, TVB-2640, is currently being tested for its effect on mammary, colon, prostate, and lung tumors and leukemia (clinicaltrials.gov)." (PMID 30250408, 2018). "We identified the K562 leukemia cell line as having the highest PKLR expression using our recently published data in Cell Atlas and treated the cell line with C75, a FASN inhibitor, at different concentrations for 24 h." (PMID 28827398, 2017). "The relative low expression of ACLY, ACC, and FASN in GC-resistant NALM-6/HDR cells pointed out that targeting FAS might not a good idea for certain patients of relapsed/refractory leukemia." (PMID 34823530, 2021).
non-alcoholic steatohepatitis (15 papers, 2010 to 2025). "Fatty acid synthase inhibitors, exemplified by denifanstat, show promise in metabolic dysfunction-associated steatohepatitis (MASH)." (PMID 41011192, 2025). "Various FASN and ACC inhibitors are in development, primarily for cancer and metabolic dysfunction-associated steatohepatitis (MASH)." (PMID 41280910, 2025). "A preclinical study suggests that TVB3664, a novel FASN inhibitor, significantly ameliorates the fatty liver phenotype, although TVB3664 monotherapy shows moderate efficacy in metabolic dysfunction-associated steatohepatitis (MASH)-related murine HCCs110." (PMID 40025169, 2025). "Fatty acid synthase (FASN) is an attractive therapeutic target in non-alcoholic steatohepatitis (NASH) because it drives de novo lipogenesis and mediates pro-inflammatory and fibrogenic signaling." (PMID 36123383, 2022). "TVB‐2640 is a FASN inhibitor currently being used for the treatment of non‐alcoholic steatohepatitis in a clinical phase II trial." (PMID 33665967, 2021). "Supporting this notion, we and others have found that serum FASN concentration is increased in patients with non-alcoholic steatohepatitis or chronic liver impairment." (PMID 20707918, 2010). "Thus, targeting FASN provides a new strategy for treating non‐alcoholic steatohepatitis." (PMID 40621620, 2025). "PTGS2 (degree = 14) amplifies inflammatory cascades by converting FASN-derived arachidonic acid into protumorigenic prostaglandin E2, establishing a self-perpetuating lipid-inflammation feedforward loop that drives IL-6/STAT3-mediated malignant transformation in non-alcoholic steatohepatitis." (PMID 40839202, 2025). "Hepatic mRNA expression of FASN, the enzyme for de novo lipogenesis, and its transcription factor [sterol regulatory element-binding protein-1c (SREBP-1c)], has been reported to be upregulated in MASLD, but not in metabolic dysfunction-associated steatohepatitis (MASH) in murine models." (PMID 39351533, 2024). "TVB-2640, a highly potent and selective FASN inhibitor, was designed to reduce hepatic fat in nonalcoholic fatty liver disease (NAFLD) and nonalcoholic steatohepatitis." (PMID 35898882, 2022).
Hyperinsulinemia (14 papers, 2013 to 2025). An increased concentration of insulin in the blood. "In addition to leptin resistance, hyperinsulinemia also contributes to the obesity phenotype in these mice, at least in part, by inducing hypothalamic FASN level and activity, which in turn, causes hyperphagia and lower physical activity." (PMID 28184213, 2017). "Among the known regulators of FASN expression are hyperinsulinemia, elevated serum triacylglycerols, and NEFAs, all of which are increased in obesity and thus result in augmented lipogenesis." (PMID 37602323, 2023). "Since the rise of hypothalamic FASN activity mediates hyperphagia independently of leptin, it is likely that hyperphagia is sustained by hyperinsulinemia-driven increase in hypothalamic FASN activity in Cc2−/− mutants." (PMID 31266142, 2019). "Hyperinsulinemia can also induce FASN activity in the liver." (PMID 31266142, 2019). "Moreover, hyperinsulinemia in Ceacam1−/− mice induces hypothalamic FASN level and activity, which contributes to hyperphagia and physical inactivity." (PMID 30314283, 2018). "Under obese condition, hyperlipidemia and hyperinsulinemia repress RIMKLA to impair BHMT1 activity and elevate Hcy level, which activates AP1 to induce the transcriptions of FASn and CD36, stimulating de novo lipid synthesis and uptake." (PMID 39117631, 2024). "Nonetheless, hyperinsulinemia induces the transcriptional activity of SREBP-1c to stimulate the expression of lipogenic genes, such as fatty acid synthase (FASN), followed by their activation." (PMID 31266142, 2019). "Both DHA and EPA groups had liver lipid similar to baseline, however, DHA was more effective than EPA for reducing hepatic fatty acid synthase (FAS), increasing the proportion of smaller lipid droplets, reversing early fibrotic damage, and reducing fasting hyperinsulinemia." (PMID 31022865, 2019). "The state of hyperinsulinemia increases the activity of SREBP in the liver, thereby increasing the levels of lipogenic genes, such as fatty acid synthase (FAS), acetyl-CoA carboxylase (ACC) and Stearoyl-CoA Desaturase1 (SCD1) contributing to the buildup of hepatic fat." (PMID 23496920, 2013).
hyperlipidemia (13 papers, 2014 to 2024). "DBP can activate the PPARα signaling pathway and affect the expression of fatty acid synthase, sterol regulatory element binding proteins, and glycerol-3-phosphate acyltransferase to cause hyperlipidemia and abnormal liver function." (PMID 35778735, 2022). "Investigations on energy metabolic mechanism demonstrates that the hyperlipidemia mitigating capacities of AB-SCF are up-regulated on lipoprotein lipase, AMPK, p-AMPK and down-regulated at fatty acid synthase." (PMID 34867418, 2021). "JWFT normalized hepatic fatty acid composition of hyperlipidemia rats by up-regulating hepatic acetyl-CoA carboxylase (ACC), stearoyl-CoA desaturase 1 (SCD1) and fatty acid synthase (FAS) gene expression, and down-regulating carnitine palmitoyl transferase-1 (CPT1)." (PMID 25055996, 2014). "In addition, melatonin markedly decreased activities of the hepatic lipogenic enzymes, acetyl-CoA carboxylase (ACC) and fatty acid synthase (FAS) (p < 0.05), and elevated the relative hepatic carnitine palmitoyltransferase-1α expression in hamsters with HFD-induced hyperlipidemia." (PMID 30935037, 2019).
lymph node metastasis (13 papers, 2018 to 2026). "The expression of SREBF1 and FASN proteins was significantly associated with a higher level of lymph node metastasis in IMPC (SREBF1, R = 0.405, P = 0.000; FASN, R = 0.521, P = 0.000)." (PMID 34799559, 2021). "FASN levels were clearly upregulated in CRC tissues with high expression of FASN significantly associated with lymph node metastasis, liver metastasis, TNM (tumor, node, metastasis) stage, and poor prognosis." (PMID 33194695, 2020). "Positive expression of MET and FASN were significantly correlated with lymph node metastasis, pathological TNM, and pathological Stage." (PMID 34123778, 2021). "Positive expression of MET and FASN were correlated with lymph node metastasis, pathological TNM, and pathological Stage." (PMID 34123778, 2021). "High expression of FASN could predict poor prognosis in CC patients and was correlated with lymph node metastasis." (PMID 35597782, 2022). "In another report, high FASN was significantly correlated with lymph node metastasis but not with pathological stage, ki-67 index, diseasefree survival, and overall survival in patients with TNBC." (PMID 39333940, 2024). "Furthermore, FASN siRNA inhibited the growth of in vivo oral SCC and lymph node metastasis, and FASN inhibitors increased the sensitivity to radiotherapy." (PMID 36185215, 2022). "To know the relationship of MET and FASN with the clinical pathological features, we carried out the correlation analysis and found that the positive expression of MET and FASN were significantly correlated with lymph node metastasis, pathological TNM, and pathological Stage." (PMID 34123778, 2021).
nasopharyngeal carcinoma (12 papers, 2019 to 2025). A carcinoma arising from the nasopharyngeal epithelium. "Adenovirus encoded short hairpin RNA knockdown of HOTAIR causes the decrease of free fatty acid and FASN at transcriptional and post-transcriptional levels in nasopharyngeal carcinoma cells." (PMID 31850189, 2019). "Notably, FASN enzyme production has been implicated in inducing radioresistance in nasopharyngeal carcinomas in previous studies, further highlighting the intricate interplay between ferroptosis regulation and radioresistance mechanisms in HNCs." (PMID 40143107, 2025). "In human nasopharyngeal carcinoma cells, knockdown of HOTAIR causes a decrease in free fatty acids and FASN at the transcriptional and posttranscriptional levels." (PMID 35036050, 2022). "The results from cell lines and clinical tissues demonstrate that long intergenic non-protein-coding RNA 02570 can adsorb miRNA-4649-3p to upregulate SREBP-1 and FASN, which promotes the progression of nasopharyngeal carcinoma (NPC)." (PMID 35912181, 2022). "The role of FASN as a direct tumor oncogene has not been well understood so far, as it promotes tumor cell growth in breast and nasopharyngeal cancer." (PMID 34885085, 2021). "Additionally, some studies have demonstrated that inhibiting the FASN gene significantly increases nasopharyngeal carcinoma cell sensitivity to radiotherapy." (PMID 38189049, 2023). "In addition, EGCG has been shown to enhance the nasopharyngeal carcinoma response to radiation therapy via the downregulation of FASN expression." (PMID 35243817, 2022). "During EBV latent infection in nasopharyngeal carcinoma (NPC) cells—cells of epithelial origin—there is increased FASN expression as compared to uninfected NPC cells." (PMID 30699959, 2019). "In human nasopharyngeal carcinoma cells, high expression of HOTAIR is positively correlated with FASN expression." (PMID 31850189, 2019). "Interestingly, GSTM3 was found to confer radiosensitivity to nasopharyngeal carcinoma cells in vitro by inhibiting the expression of GPX4 and influencing the production of PUFAs by indirectly increasing polyunsaturated fatty acid production via fatty acid synthase (FASN) enzyme stability." (PMID 40143107, 2025). "Furthermore, a recent study demonstrated that LMP1 upregulates FASN and lipogenesis in EBV-positive nasopharyngeal carcinoma (NPC)." (PMID 33208446, 2021).
liver disease (11 papers, 2017 to 2025). "The expression of AP-2α correlated negatively with the expression of WTAP, YTHDC1 and FASN in liver disease samples." (PMID 40180937, 2025). "Based on the heterogeneity of physiological and pathological properties of FASN, it is more emergent to identify new FASN regulators to combat liver disease-related metabolism." (PMID 40180937, 2025). "Liver diseases connected to FASN can thus be treated (by silencing PKLR, PCSK9 or PNPLA3) without experiencing the side effects associated with direct FASN inhibition." (PMID 28827398, 2017). "A. cinnamomea may also exert metabolic benefits relevant to the progression of liver disease, particularly through the inhibition of fatty acid synthase (FAS), which reduces hepatic triglyceride accumulation and lipid droplet formation." (PMID 40563294, 2025). "Although FASN has been extensively studied in tumors and liver diseases, research regarding its role in autoimmune diseases remains unclear." (PMID 40125636, 2025). "Clinically, AP-2α expression negatively correlates with the expression of FASN, WTAP, YTHDC1 and the development of liver disease." (PMID 40180937, 2025). "We also wanted to analyze the effects of purified C. difficile-derived MVs on other key processes in the development of various liver diseases, such as the β-oxidation (CPT1A) and synthesis of fatty acid (FASN)." (PMID 37107193, 2023).